HEXA (hexosaminidase subunit alpha)
Diseases named in the same sentence as HEXA in open-access papers (continued):
Sharing a sentence is not in itself a finding about the gene and the disease.
cancer (5 papers, 2014 to 2025). A tumor composed of atypical neoplastic, often pleomorphic cells that invade other tissues. "Thirty-seven significantly associated cancer–gene pairs and four genes (GBA1, SGSH, HEXA, and CLN3) with a Pan-Cancer association were identified (Pan-Cancer is a cohort of 2567 patients with cancer)." (PMID 39404425, 2024). "These included homozygous variants calls in genes related to cancer (BRCA1, APC, MEN1), congenital malformation syndromes (TCOF1), metabolic deficiencies (FBP1, HEXA), and neurological diseases (FUS, MLC1, DMD)." (PMID 26547235, 2015). "While still largely unexplored in cancer cells, the formation of paucimannosidic N-glycans through an only recently discovered truncation pathway involves most critically the HEXA and HEXB among other glycoside hydrolases to form M3(F) and further truncated structures." (PMID 39947398, 2025). "Moreover, HEXA, HEXB, MAN2A1, and MAN2B1 were overexpressed in cancer relative to healthy stomachs from individuals without gastric pathologies." (PMID 41041068, 2025).
tumor (4 papers, 2017 to 2025). "Several glycoproteins associated with the lysosomal pathway, including LAMP1, ASAH1, ATP6AP1, and HEXA, exhibited significantly increased levels of specific glycoforms bearing high-mannose glycans in tumor tissue." (PMID 41061966, 2025). "A high abundance of HexA (p = 0.0089), HexA–HexNAc (p = 0.0026), and HexNAc–HexA–HexNAc (p = 0.0132) in tumor cell regions resulted in a poor prognosis." (PMID 28978092, 2017). "Similarly to GM2A depletion, loss of either HEXA or HEXB decreased GSC growth and abolished tumor sphere formation." (PMID 35133980, 2022).
infection (1 paper, 2015). The state of being infected such as from the introduction of a foreign agent such as serum, vaccine, antigenic substance or organism. "The RovM homologs LrhA and HexA of the insect pathogens, P. temperata and X. nematophila, regulate expression of virulence factors, immuno-suppression and metabolic usage during infection of their respective insect hosts." (PMID 26348850, 2015).
HEXA also shares sentences with these, for which no sentence is quoted: GM1 gangliosidosis (4 papers); deafness (2); Fabry disease (2); neurological diseases (2); Parkinson disease (2); sickle cell anemia (2); sphingolipidoses (2); Tremor (2); tuberculosis (2); Alzheimer disease (1); Angelman syndrome (1); Anxiety (1); autosomal recessive disease (1); Batten disease (1); Bloom syndrome (1); breast carcinoma (1); cerebellar ataxia (1); CLN2 disease (1); CLN5 disease (1); Cognitive impairment (1); congenital ichthyosis (1); congenital malformation syndromes (1); cortical blindness (1); cyst (1); cystic fibrosis (1); diabetic nephropathy (1); focal segmental glomerulosclerosis (1); frontotemporal dementia (1); Gaucher disease type I (1); genetic diseases (1).
A further 36 diseases each share a sentence with HEXA in 1 paper.